PXN (paxillin)
Diseases named in the same sentence as PXN in open-access papers (continued):
Sharing a sentence is not in itself a finding about the gene and the disease.
breast carcinoma (continued). "PXN, which is an intracellular adaptor protein connecting integrins for signal transduction into the cell, has been estimated to be upregulated in various cancer types, including lung cancer, gastric cancer, and breast cancer." (PMID 34977001, 2021). "However, in some types of cancers, downregulation of PXN was reported, e.g., breast cancer, colorectal cancer, leukemia, and low-grade glioma." (PMID 34946859, 2021). "Notably, high PXN gene expression was significantly correlated with poor DMFS in breast cancer (P < 0.01)." (PMID 34135128, 2021). "Reduced FAK, paxillin, and vinculin levels supported the findings of reduced filopodia and lamellipodia in 4T1 breast cancer cells, which might have resulted in reduced cancer cell migration as visible from large wound size in wound-healing assay." (PMID 34535685, 2021). "Previous studies have shown functional links between PXN and tumorigenesis, such as oral cavity squamous cell carcinoma, gastric cancer, lung carcinoma, colorectal cancer, glioblastoma, breast cancer, and renal cell carcinoma." (PMID 34135128, 2021). "PIGT and its gene products have been hypothesized to play a role in growth of breast cancer via paxillin phosphorylation." (PMID 32396573, 2020). "Here, we also demonstrated that RhoA/ROCK1 signaling may play an important role in activation of FAK/Src/paxillin signaling, which was similar to the molecular mechanism of the hypoxia-induced breast cancer cell migration." (PMID 31558699, 2019). "This indicates the importance of targeted PXN knockdown in 4T1 induced breast cancers." (PMID 31269666, 2019). "In summary, our data provides new mechanistic insights into the role of Rab7 in targeting Y118 site-specific phosphorylation of paxillin to the autophagy pathway to promote focal adhesion turnover in human breast cancer cells, a process essential for cell locomotion." (PMID 28415719, 2017). "Since HER2 overexpression has been involved in metastatic cancer progression, particularly in breast cancer, paxillin has been identified as a marker of aggressive breast cancer and a promoter of neoplastic growth and invasion, supporting its role as a biomarker or therapeutic target." (PMID 28214467, 2017). "Interference with the Rab7-paxillin-autophagy regulatory network using genetic and pharmacological approaches greatly impacted focal adhesion stability, cell locomotion and progression to metastasis using a panel of human breast cancer cells." (PMID 28415719, 2017). "Paxillin expression levels are known to correlate with HER2 levels in breast cancer cells and patient samples and thus may be a predictor of therapeutic efficacy." (PMID 26980710, 2016). "Similarly, MAP3K11 was found to be required for chemokine-induced invasiveness of breast cancer cells through its activation of paxillin." (PMID 26717044, 2016). "Paxillin was also previously studied in breast cancers but with different outcomes." (PMID 25955236, 2015). "Additionally, enhanced paxillin phosphorylation has been observed in breast cancer cells derived from mouse lung metastases." (PMID 25337707, 2014). "In breast cancer, it has been found that the overexpression of paxillin may represent a useful prognosticator and be employed to predict the clinical response to chemotherapy." (PMID 24348846, 2014). "Additionally, breast cancer cells derived from mouse lung metastasis have exhibited an enhanced level of paxillin phosphorylation." (PMID 24023938, 2013). "Paxillin and cortactin are relatively abundant proteins in most cultured cells, including both invasive and noninvasive breast cancer cells, and levels of the AMAP1 expression seem to be crucial for formation of this trimeric protein complex at detectable levels." (PMID 19416474, 2009).
breast carcinoma (continued). "Taken together, our results provide direct evidence that Fyn-mediated paxillin Tyr31 phosphorylation is required for breast cancer migration and invasion, suggesting that targeting paxillin Tyr31 phosphorylation could be a potential therapeutic strategy for mitigating breast cancer metastasis." (PMID 37958964, 2023). "Thus, targeting paxillin Tyr31 phosphorylation could be a promising therapeutic strategy for the treatment of breast cancer metastasis." (PMID 37958964, 2023). "Additionally, progesterone receptor B signaling could negatively regulate breast cancer cell migration and metastasis by affecting the Cyclin-D1/Cdk4/Paxillin interaction and Paxillin phosphorylation." (PMID 36869991, 2023). "Paxillin can regulate the integrity and contractility of E-cadherin-dependent junctions by controlling the balance of RhoA and Rac1 activities to regulate the integrity of cell–cell adhesion junctions, thereby maintaining the migration of breast cancer cell populations." (PMID 37175948, 2023). "Moreover, it is worth noting that recent research indicates that some molecules in cell–cell junction structures have little effect on primary tumour initiation and growth, but they are instead critical for the formation of distant metastases, such as paxillin in breast cancer." (PMID 36291586, 2022). "However, a low PXN expression level correlated with poor RFS in breast cancer (P < 0.001)." (PMID 34135128, 2021). "In this study, we uncovered an essential role of Y118 site-specific tyrosine phosphorylation of paxillin, an adapter protein of focal adhesion complexes, in paxillin recruitment to autophagosomes to trigger turnover of peripheral focal adhesions in human breast cancer cells." (PMID 28415719, 2017). "Phosphorylation of FAK/PTK2 and its downstream effectors, P130Cas and paxillin, was reduced in defactinib-treated JIMT-1 and MDA-MB-231 breast cancer cell lines compared with DMSO-treated cells." (PMID 41148501, 2026). "In breast cancer, ASAP1 interacts with the SH3 domain of cortactin via its proline‐rich sequence and binds to paxillin via its own SH3 domain, playing a role in promoting invasion." (PMID 40742091, 2025). "It is reported that ITGAV silencing inhibits cell proliferation, invasion and self-renewal of breast cancer cell lines by altering the expression of BCL2 apoptosis regulator (BCL2) and paxillin (PXN)." (PMID 38374893, 2024). "It is reported that ITGAV silencing inhibits cell proliferation, invasion, and self-renewal of breast cancer cell lines by altering the expression of BCL2 and PXN (Cheuk, Siu, 2020)." (PMID 38374893, 2024). "Axon guidance signalling proteins Paxillin (PXN) and Reticulon4 (RTN4) showed increased abundance, while GIT1, GRB2 and SHRANK2 showed decreased abundance in breast cancer cells after co-culture." (PMID 39232464, 2024). "Tyrosine 40 in the LIR domain of paxillin is a target of SRC kinase; SRC increases the LC3B–paxillin interaction and promotes the migration of breast cancer cells." (PMID 36831154, 2023). "At the same time, Cucurbitacin B, which has strong anticancer activity, can inhibit the metastasis of breast cancer by inhibiting the phosphorylation of FAK and paxillin and destroying the FAK/paxillin signaling pathway." (PMID 37175948, 2023). "As a breast cancer tumor suppressor, interferon-inducible protein IFIX overexpression can stabilize the cytoskeleton through various cytokeratins and downregulate paxillin to inhibit the invasiveness of human tongue squamous cell carcinoma in vitro." (PMID 37175948, 2023). "Studies indicated that LIPH had a higher expressed level in breast tumor tissue, and it affected the distant metastasis of breast cancer by regulating CAPN2 and paxillin." (PMID 37745080, 2023).
breast carcinoma (continued). "In breast cancer cells transfected with plasmids overexpressing active or inactive ASAP3, cellular vinculin or paxillin in focal adhesion and the distribution of invadopodia were not affected." (PMID 36382054, 2022). "A study using animals injected via the tail vein with sublines of highly metastatic breast cancer cells reported that inhibition of GIT1 expression reduced cell migration/invasion and lymph node metastasis through FAK and paxillin signalling." (PMID 35318302, 2022). "VEGF is highly expressed in breast cancer cells and VEGF/FAK/Paxillin pathway contributes to the metastasis of breast cancer." (PMID 33903672, 2021). "Studies found that MLK3 enhanced the phosphorylation of the focal adhesion protein paxillin on Ser 178 and Tyr118, and inhibition of MLK3/JNK/paxillin signaling axis decreased Rho activity to block focal adhesion turnover and migration of breast cancer cells." (PMID 33407478, 2021). "In this context, conditioned-medium (CM) derived from adipocytes was demonstrated to increase the wound closure rate of breast cancer cells through both activation of FAK and paxillin and their colocalization at FAs complex." (PMID 33562737, 2021). "Suppression of ITGAV inhibited cell growth, invasion, and self-renewal of breast cancer by altering BCL2 and PXN levels." (PMID 34249086, 2021). "In breast cancer, lung cancer, neuroblastoma, ovarian cancer, and hepatocellular carcinoma, studies have confirmed that FAK–Src–Paxillin cascade pathway modulates tumor cell proliferation, migration, and metastasis." (PMID 32513911, 2020). "Silencing of ITGAV inhibited cell proliferation, invasion, and self-renewal of breast cancer cell lines by altering expression of BCL2 and PXN." (PMID 32847144, 2020). "In the current study, we successfully targeted dysregulated CTNNA1, CTNNB1, TLN1, VCL, PXN, and ACTN1 genes by delivering respective siRNAs with the help of nano-sized CA particles in breast cancer cells as well as in a murine breast cancer model." (PMID 31269666, 2019). "Approximately 90% of the primary breast cancers overexpressed HER3, p-mTOR, p-4EBP1, p-JAK2, p-STAT3, and 50% overexpressed p-Paxillin." (PMID 31667338, 2019). "OC-LP Combination significantly inhibited invasion and migration of breast cancer cells through reduced activation of focal adhesion kinase (FAK) and paxillin." (PMID 30781364, 2019). "In this study, we have provided evidence that SUMOylated PYK2 enhances motility of MDA-MB-231 metastatic breast cancer cells via signaling through the SRC, paxillin, and ERK1/2 signaling cascade." (PMID 29438996, 2018). "The main goal of this study was to assess inhibition of tumor angiogenesis by nobiletin in estrogen receptor positive (ER+) breast cancer cells via Src, FAK, and STAT3-mediated signaling through PXN." (PMID 28468300, 2017). "This study demonstrated that EL inhibited breast cancer cell migration and invasion by decreasing levels of phosphorylated FAK at tyrosine 397 (Y397) and phosphorylated paxillin." (PMID 28068967, 2017). "A reduction in FAK and paxillin phosphorylation and a corresponding inhibition of adhesion were also observed in SKBR3 breast cancer cells transfected with inducible DCYTB." (PMID 28270217, 2017). "Particularly, the phosphorylation of paxillin at Ser178 carried by JNK has been shown to regulate migration of cells from rat bladder tumors, hamster ovary, and human mammary cancer, as well as the extension of neurites in mouse neuroblastoma cells." (PMID 28214467, 2017). "In breast cancer, MLK3 signals through paxillin, which has been shown, in other settings, to activate p190RhoGAP." (PMID 27213454, 2016).
breast carcinoma (continued). "Similar to our observations in breast cancer cells, cellular attachment to fibronectin induces MEKK2 to co-localize with paxillin in areas of the cells that are consistent with focal adhesions." (PMID 27096002, 2015). "Our data clearly shows inhibition of ILK1, paxillin, Akt, ERK and Rho kinases while inducing GSK3β by CuB treatment in breast cancer cells." (PMID 24729020, 2014). "These include p190RhoGAP, Rho, RAS, Rac1, Paxillin, p38MAPK, and ERK5 in breast cancer, and AKT, GSK3β, and βCatenin in esophageal cancer." (PMID 24788754, 2014). "In fact, the invasiveness of breast cancer cells correlates with the formation of a ternary complex between PKD1, cortactin and paxillin in invadopodia-enriched membranes." (PMID 25287328, 2014). "In breast carcinoma, neutrophils were shown to cluster tumoral ICAM-1 and phosphorylate FAK (focal adhesion kinase) and paxillin via src, as well as p38-MAPK via Rho-GTPase." (PMID 23423155, 2013). "Additionally, nobiletin has been discovered to impede cancer angiogenesis in mammary carcinoma showing estrogen receptor positivity by restraining the signaling mediated by Src, FAK, and STAT3 while fostering PXN gene expression." (PMID 38611849, 2024). "In another study, it was also demonstrated that PXN expression was not correlated with the invasiveness and tumor grade in breast carcinomas, although it was involved in the malignant transformation of breast epithelium." (PMID 38962075, 2024). "Furthermore, the phosphorylation of paxillin tyrosine residue 31 (Tyr31) was significantly increased upon the TGF-β1-induced migration and invasion of breast cancer cells." (PMID 37958964, 2023). "In the prostate cancer cell line PC-3 osteolytic model and the mixed osteolytic/osteogenic LNCaP model, paxillin knockdown resulted in reduced matrix adhesion and a general increase in cell invasion, but the opposite occurred in the MDA-MB-231 breast cancer model." (PMID 37175948, 2023). "To clarify the role of paxillin Tyr31 phosphorylation in the migration and invasion of breast cancer cells, we generated a non-phosphorylatable paxillin Tyr31 mutant by replacing the tyrosine residue with phenylalanine (Y31F)." (PMID 37958964, 2023). "Therefore, ST inhibitors inhibit breast cancer growth by inhibiting integrin expression and the phosphorylation of FAK and paxillin." (PMID 37175948, 2023). "In tumor metastasis, salvicine influences the cell adhesion genes and decreases the expressions of different integrin proteins, i.e., integrin a3/a6/aE/b3/b5/b8, paxillin, and focal adhesion kinase (FAK), in human breast cancer; its anti-metastatic efficiency has also been suggested." (PMID 35719997, 2022). "Moreover, both OA derivatives significantly reduced migration of HER2-positive SK-BR-3 breast cancer cells and this effect was mediated by modulation of the integrin β1/FAK/paxillin pathway." (PMID 34681931, 2021). "Breast cancer cells treated with T3 triggered a significant increase of phospho-paxillinTyr118 at the cell membrane periphery where cortical actin complexes were formed, and this was impaired by the blockade of Src (PP2), FAK (FAKi), and paxillin (siRNAs)." (PMID 30899247, 2019). "Within this pathway, cell migration of breast cancer cells is prevented by RA through the regulation of the expression of Moesin and the downstream inhibition of Src, FAK, and paxillin activity, providing novel mechanistic clues for the development of new drugs for cancer treatment." (PMID 28214467, 2017). "In addition, transfection of Xcad-11-EGFP into HeLa (cervical cancer cells), MCF-7 (breast cancer cells) and murine NIH 3T3 fibroblasts revealed Xcad-11 localization to peripheral FA, where it co-localized with paxillin and F-actin." (PMID 26952325, 2016).
breast carcinoma (continued). "Using this model of GFP-LIMK1 targeted to distinct subcellular compartments in MDA-MB-231 breast cancer cells, we found that both nuclear- and cytoplasmic-targeted GFP-LIMK1 enhanced FAK/paxillin/Src/AKT/Erk signaling, increased cellular invasion, and promoted xenograft tumor growth in nude mice." (PMID 21682918, 2011). "Additionally, the non-phosphorylatable mutant of paxillin at Tyr31 reduces actin stress fiber formation, migration, and invasion of breast cancer cells." (PMID 37958964, 2023). "Interestingly, WT paxillin, but not Y31/118F paxillin mutant, was localized in the centrosome of non-mitotic breast cancer cells and U2OS cell." (PMID 31101859, 2019). "Additionally, in non-mitotic breast cancer cells, paxillin was required for centrosome cohesion, which may be associated with cell polarity during migration." (PMID 31101859, 2019). "Furthermore, paxillin knockdown in breast cancer cells was shown to disrupt Golgi complex localisation and cell reorganisation as a result of an increase in HDAC6 activity in the absence of paxillin." (PMID 39941046, 2025). "The predicted negative scores for PI3/AKT and paxillin signaling pathways correlate well with literature-validated OC anti-invasive activity through downregulating PI3/AKT and paxillin signaling pathways in breast cancer." (PMID 32545325, 2020).